TNF (tumor necrosis factor)
Diseases named in the same sentence as TNF in open-access papers (continued):
Sharing a sentence is not in itself a finding about the gene and the disease.
colitis (continued). "This study demonstrated, that the PDE4 inhibitor roflumilast and the PDE3/PDE4 inhibitor pumafentrine dose-dependently ameliorated the clinical score and colonic TNFα production in murine DSS-induced colitis in a preventive setting, while not affecting the histopathologic colonic findings." (PMID 23468885, 2013). "Decreased or absent TNF production alone was not sufficient to result in colitis." (PMID 22848611, 2012). "Thus, we believe that the absence of TNF signaling via TNF-R1 or 2 affects neutrophil recruitment differently into colonic tissues upon the establishment of colitis." (PMID 23285227, 2012). "Also, both CLA and VSL#3 suppressed colonic mRNA expression of TNF-α and MCP-1, indicating that the protective effect against DSS colitis may be due to a decrease in macrophage recruitment." (PMID 22363592, 2012). "Indeed, we found that in the IL-10−/− mice there was an overproduction of IFN-γ and IL-17, whereas in DSS-induced model of colitis occurred a prevalence of IL-6, TNF-α, and INF-γ without alterations in IL-17 production (data not shown)." (PMID 22400037, 2012). "In particular, we focused on the contribution of TNF-α and colonic mucin in innate host defense prior to epithelial cell damage and investigated whether TNF-α neutralizing antibody can alter disease onset and/or progression in DSS-induced colitis in rats." (PMID 21949848, 2011). "Furthermore BTZO-15 reduced the ulcerated area and rectal MPO activity in 2,4,6-trinitrobenzene sulfonic acid (TNBS)-induced colitis rats without affecting rectal TNF-α levels." (PMID 21853095, 2011). "THSG appears to exert its beneficial effects on acetic acid-induced experimental colitis through upregulation of PPAR-γ mRNA and protein levels and inhibition of the NF-κB pathway, which in turn decreases the protein overexpression of the downstream inflammatory mediators TNF-α, IL-6 and COX-2." (PMID 21993246, 2011). "The protective effects of IG on dextran sulfate sodium (DSS)-induced colitis were assessed by macroscopic score and histological analysis as well as by determination of inflammation markers such as MPO activity and the mRNA expressions of pro-inflammatory cytokines such as TNF-α and IL-8." (PMID 21931839, 2011). "The improvement in colitis symptoms is unlikely to be related to the increased production of TNF-α but instead might reflect a change in the composition of the bacterial microflora that has been shown to impact disease symptoms in the DSS model." (PMID 19232107, 2009). "Therefore, our data provide new hints for an immune-regulating rather than immune-activating role of IL-6 in the colitis model of IL-2−/−-mice suggesting that IL-6 in the absence of TNF-α, IL-12 and IFN-γ exerts anti-inflammatory effects." (PMID 18545662, 2008). "Furthermore, colonic TNF levels were not elevated in untreated control mice with chronic DSS colitis, despite the presence of very severe colonic inflammation (histologic scores of 52 ± 3; n = 10)." (PMID 18331642, 2008). "The TNF levels in colon tissue measured in a subset of these mice (n = 5) was 72 ± 3 pg/100 mg tissue, which is similar to that seen in control wild type mice without colitis." (PMID 18331642, 2008). "Taken together with the lack of efficacy of LMP-420 in acute or chronic DSS colitis despite its ability to significantly lower colonic TNF levels, these data suggest that elevated levels of TNF are not required for the initiation and maintenance of colonic inflammation in this murine model." (PMID 18331642, 2008). "In another animal study, failure to detect local or systemic TNF and failure to prevent colonic inflammation with anti-TNF antiserum have pointed that TNF could not be an inflammatory mediator in DSS-induced murine colitis." (PMID 17069659, 2006).
colitis (continued). "Additionally, in vagal ganglia from DSS-colitis mice, there was a specific downregulation of inflammatory signaling pathways, including those related to chronic inflammatory response, cell surface receptor signaling pathway via JAK-STAT, cellular response to TNF, and response to cytokine." (PMID 40268933, 2025). "Furthermore, Fuzhuan tea crude extract significantly decreased TNF-α, IL-1β and IFN-γ inflammatory cytokines’ levels, and significantly reduced myeloperoxidase activity, nitric oxide, and malondialdehyde levels in colon tissue, thus improving DSS-induced colitis in mice." (PMID 39272608, 2024). "The combination of Radix Astragali polysaccharides with CP polysaccharides in a mouse model of colitis could improve colitis symptoms in mice by elevating SOD, decreasing MDA to improve antioxidant activity, and simultaneously decreasing the expression of inflammatory factors TNF-α, IL-1β, and IL-6." (PMID 38803438, 2024). "Thus, IEC lacking caspase-8 or FADD due to epithelial cell-specific deletion underwent RIPK3-dependent necroptosis instead of apoptosis in response to TLR or TNF stimulation, leading to a complete absence of Paneth cell, serious tissue damage, enteritis and severe erosive colitis in vivo." (PMID 39840043, 2024). "When rats with experimental colitis, induced by administering 3% acetic acid intra-rectally, were treated with P. lentiscus mastic oil, administered intra-rectally, a statistically significant decrease in TNF-α level after 7 days was observed, while IL6 did not change." (PMID 37569412, 2023). "Interestingly, despite the theory that proinflammatory cytokines are the main inducers of MCP-1, our analysis of TNFα expression during colitis development and resolution showed almost a 2-fold reduced TNFα mRNA level in CD26−/− mice compared to C57BL/6 animals in the acute phase of colitis." (PMID 35628317, 2022). "Therefore, to examine whether MLN DCs from Yeti/CD1d KO mice show proinflammatory phenotypes during DSS-induced colitis, we compared proinflammatory cytokine production (i.e., IL12, TNFα, and IL6) by both splenic DCs and MLN DCs from WT, Yeti, CD1d KO, and Yeti/CD1d KO mice during DSS treatment." (PMID 36499642, 2022). "In this study, we used ELISA to detect the contents of cytokines IL-1β, IL-6, TNF-α, IL-12, and TGF-β in mouse intestinal tissue, and we found that QYJD could significantly reduce the contents of IL-1β, IL-6, TNF-α, and TGF-β in colon tissue of mice with colitis." (PMID 36523417, 2022). "Moreover, treating mice with the potent semi-synthetic FXR ligand 6-Ethyl CDCA attenuated the severity of colitis and immune cell activation and the expression of various pro-inflammatory cytokines, such as TNF alpha, IL-1beta, and IL-6 in WT but not in FXR -/- mice." (PMID 35807844, 2022). "Strikingly, these experiments revealed that TNF produced by epithelial cells can control epithelial cell repair, colonic TNF production and IL-22BP colonic levels, while myeloid cell derived TNF contributed to severity of colitis without influencing IL-22 levels in the colon." (PMID 35383266, 2022). "Interestingly, despite the lack of clinical improvement of colitis by blocking of TNF from “non-T cells”, levels of IL-22BP were reduced upon infliximab administration, indicating that “non-T” cell derived TNF may also regulate IL-22BP production." (PMID 35383266, 2022). "In addition, PLGA MS-carried oe-circGMCL1 treatment significantly alleviated the severity of colitis, which presented as decreased DAI, reduced inflammatory cell infiltration and inflammatory scores, and decreased colonic proinflammatory cytokines (TNF-α, IFN-γ, and IL-17)." (PMID 36088391, 2022). "Taken together, these results suggest that Se-SDF could inhibit the pathogenesis of colitis in mice by promoting the release of anti-inflammatory cytokines (IL-10 in male and female mice) and suppressing pro-inflammatory cytokines (TNF-α and IL-6 in female mice, TNF-α in male mice)." (PMID 36159466, 2022).
colitis (continued). "There have been also a few papers on the effects of TNF-α pre-treatment on the therapeutic efficacy of MSCs against colitis, but most of them focused on the results of canine AT-MSCs administration in a murine colitis model, and no sufficient references currently available." (PMID 33276479, 2020). "Indeed, we found increased levels of pro-inflammatory cytokines IL-6, MCP-1, and TNF-alpha in colonic tissue of colitic mice and a normalization effect of EGCG on these cytokines, in resonance with results from previous studies of EGCG using different colitis models." (PMID 31362373, 2019). "Furthermore, the serum TNF-α, IFN-γ, IL-1β, IL-6, and IL17 were significantly increased in the colitic mice, and hMSCs treatment could reduce these inflammatory cytokines, suggesting that hMSCs alleviated the inflammatory responses in colitis mice." (PMID 31367246, 2019). "Indeed, TNF neutralization exacerbates acute injury in the dextran sodium sulfate (DSS) colitis mouse model and exogenous TNF administration could alleviate colitis in oxazolone-treated mice and attenuate the disease severity in RA." (PMID 29751683, 2018). "Interestingly, intestinal inflammation could be induced by chronic TNF expression by the IECs whereas in the T cell transfer model of murine colitis, TNF from non-T cells seems to be responsible for colitis induction." (PMID 29751683, 2018). "The expression of the proinflammatory cytokines TNFα and IL-1β and iNOS gene (chosen as a marker of chronic inflammation) in the forepaws showed an increase in the “arthritis” group whereas no significant changes were observed in the “arthritis + colitis” group." (PMID 28926599, 2017). "Seven days later, mucosal concentration of IL-1β and TNF-α in the colon of rats treated with saline after induction of colitis was still significantly elevated and reached a value around two-fold greater than that observed in saline-treated animals without colitis." (PMID 27598133, 2016). "However, it was strange that LL202 could not inhibit NF-κB signaling in DSS-induced colitis mice, but blocked NF-κB pathway activated by TNF-α in vitro." (PMID 27590510, 2016). "Administration of M. on TNBS colitis following high iron supplementation (3.0 g/Kg diet) did not improve the overall histological score and the individual histological parameters, neither reduced the levels of t-TNF-α (16.57 ± 5.61 versus 14.65 ± 3.88, P = 0.296)." (PMID 24895596, 2014). "Furthermore, TNFα was able to inhibit the up-regulation of hepcidin induced by IL-6 in the Huh7 cells, which could help to explain why hepcidin expression was decreased during DSS colitis despite increased levels of IL-6 produced by the colon." (PMID 22675442, 2012). "As TNF-α and adherent and goblet cell mucin are two major components that are altered in UC, we reasoned that both of these components play major roles in epithelial barrier function and may be selectively altered prior to epithelial cell damage in DSS-induced colitis." (PMID 21949848, 2011). "From this data we conclude that the B. vulgatus triggered IL-6 secretion by LP DC in absence of proinflammatory cytokines such as IL-12 or TNF-α induces a semi-mature LP DC phenotype, which might prevent T-cell activation and thereby the induction of colitis in IL-2−/−-mice." (PMID 18545662, 2008). "Limitations in the ability of in vivo models to represent human IBD physiology are evident, as the most commonly used anti-TNF and anti-IL-12/23p40 antibodies, which benefit patients with IBD, are generally not effective in chemically-induced colitis models." (PMID 39975910, 2025). "However, the lack of Mcpt-4 could induce significant increase of TNF-α and IL-6 in colitis mice." (PMID 40697820, 2025). "This subset has previously been observed in the mucosa of children with colitis, where CD8+ T cells can differentiate into non-classic Tc2 cells under stimulation with TGF-β in combination with IL-1β/TNF-α or IL-6, thus contributing to the disease." (PMID 40244207, 2025).
colitis (continued). "Despite not witnessing significant alterations in TNF-α and IL-10 levels in the current DSS-induced colitis model, we expect such modifications to occur with concentration and duration adjustments." (PMID 38539873, 2024). "As already mentioned in the “Cytokine” section, overexpression of IL-1β and IL-17, but not of TNF-α, has been demonstrated by two independent groups in samples from patients with ICI-induced colitis." (PMID 36900420, 2023). "In female C57BL/6 mice, nicotine (0.25 and 2.50 μmol/kg, i.p.)treatment reduced the activation of NF-κB and colonic cytokine production, including IL-6, IL-17, and TNF, but failed to reduce the disease parameters in DSS colitis." (PMID 35251010, 2022). "Our results suggest that chemogenetic inhibition of TRPV1+ neurons is not sufficient to reduce DSS-induced colitis, whereas CNO stimulation induces neurogenic inflammation in the colon, highlighted by TNF-α, IL-1β, or IL-6 upregulation." (PMID 34954381, 2022). "In TNBS-induced colitis in mice, which resembles CD, NIN decreased ISMC hyperplasia as well as expression of TNFα and IL-1β, without effect in control animals." (PMID 35715562, 2022). "Increased expression of pro-inflammatory cytokines, Il-1β, Il-6, and TNF-α, monocyte chemotactic protein-1 (Mcp-1) and macrophage inflammatory protein 2 (Mip-2), characterized DSS-induced colonic inflammation compared to non-colitic mice." (PMID 34072532, 2021). "In acute settings, regardless of organism (TNF treatment of either human or mouse epithelia, DSS colitis in the mouse), Sprouty2 levels are suppressed." (PMID 33547321, 2021). "This suggests that the apparent discrepancy in DSS colitis versus human IBD is not a species issue (for example, cells from both mice and humans downregulate Sprouty2 in response to TNF), but rather a question of acute signals that are exhausted over time." (PMID 33547321, 2021). "Dex treatment strongly upregulated the expression of the cytokines TNFα, IL-1β and IL-6 but not IL-10 in the course of DSS colitis compared with that in the control group." (PMID 32290362, 2020). "Treatment with L. brevis Bmb6 significantly suppressed the gene expression of TNF-α and IFN-γ, but not IL-1β in DSS-induced colitis mice." (PMID 32630643, 2020). "RA treatment significantly decreased the levels of TNF-α, IL-6, and IL-1β in colon tissue in WT mice during DSS-induced colitis, but the effect is not obvious in LXN−/− mice." (PMID 32555320, 2020). "The levels of IL-6, IL-17A, IL-23, TNF-α, and TGF-β1 in the colonic mucosa of colitis mice without treatment were higher than in the DSS + SSP and DSS + 5-ASA groups." (PMID 32581849, 2020). "On the other hand, RES had no significant impact on MPO activity and levels of TNF-α, PGE2, IL-6 and IL-10 in mouse models of DSS-induced colitis." (PMID 32722619, 2020). "In the absence of DSS-induced colitis, ICB efficacy was retained when anti-TNF or etanercept was co-administered." (PMID 31309173, 2019). "In particular, Infliximab, a first-generation chimeric TNF blocking monoclonal antibody, can be used in the clinic to treat ICB-induced colitis in cancer patients who do not respond to corticotherapy." (PMID 31727152, 2019). "In the ileum, TNBS treatment markedly increased IL-1β and TNF-α mRNA abundances (P < 0.05), although matrine failed to mediate TNF-α expression in TNBS-induced murine colitis." (PMID 30800071, 2019). "Specifically, colitis enhanced mRNA levels of CD86 (t7.8 = −3.2; p = 0.013) and TNF-α (t9.3 = −3.4; p = 0.006), did not change IL-1β expression, but decreased Nos2 expression (t7.092 = 5.237; p = 0.001)." (PMID 31882991, 2019). "When HT was added to diet failed to reduce the TNF-α production in paw homogenate in a murine collagen-induced arthritis and in colon tissue homogenate in a chronic DSS colitis model." (PMID 30563131, 2018).
colitis (continued). "In our study, induction of colitis did not upregulate TNF-α, which indicated that transcription of TNF-α, a major target of NF-κB activation, was not significantly involved in this colitis model." (PMID 28955126, 2017). "A further significant increase in the expression of TNF-α, IL-6 and MCP-1 mRNA was recorded in the mice with colitis fed a HFD as compared to the sedentary mice without colitis fed a HFD (p < 0.05)." (PMID 28425943, 2017). "Colonic inflammation represented by proinflammatory cytokines TNF-α and INF-γ, involved in innate immunity, and the anti-inflammatory cytokine IL-10, was not altered in the mild colitis group, compared to the control." (PMID 27957238, 2016). "In fact, mRNA levels of Tumor Necrosis Factor-α (Tnfα) and Interleukin-1β (data not shown) were even increased in the colon mucosa of Abcb4−/− mice, further ruling out the hypothesis that reduced inflammation can be the mechanism of protection in the colitis carcinogenesis model." (PMID 27995969, 2016). "The results show that MMF significantly inhibited mRNA expression of pro-inflammatory cytokines IFN-γ, TNF-α, IL-12, IL-6, and IL-1β in mice with TNBS-induced colitis; however, MMF did not inhibit the expression of IL-10 mRNA." (PMID 26561804, 2015). "We found that anti-TNF-α, antibiotics, anti-IL-12p40, anti-α4β7 integrin, CTLA4-Ig, and anti-IL-6 effectively prevented onset of colitis, whereas TNFR-Fc and cyclosporine did not." (PMID 22536543, 2012). "TNFα inhibited hepcidin expression in cultured hepatocytes and non-colitic mice, while TNFα neutralization during DSS colitis increased it." (PMID 22675442, 2012). "Serum TNF-α was up-regulated in rats with TNBS-induced colitis, and BTZO-15 did not affect TNF-α levels." (PMID 21853095, 2011). "MLN and LP, but not PP or spleen, contained higher numbers of TNF-α+ and IFN-γ+ neutrophils during Mycobacteria-enhanced colitis." (PMID 18533024, 2008). "Taken together, these studies demonstrate that short-term treatment with a transcriptional inhibitor of TNF production does not decrease the severity of acute and chronic DSS colitis or piroxicam-accelerated colitis in IL-10-/- mice." (PMID 18331642, 2008). "As we saw for acute DSS colitis, LMP-420 treatment (5 mg/kg i.p. and 41 mg/kg oral) significantly decreased colonic TNF levels in a setting where TNF was elevated in the colons of mice that did not receive this drug." (PMID 18331642, 2008). "In the current study, the serum levels of IL-6 and TNF-α were prominently increased in DSS-induced colitis mice (p < 0.0001), which were significantly decreased after RL5 supplementation (p < 0.01), but RP6 did not significantly inhibit the alterations of TNF-α." (PMID 39594091, 2024). "Priming with these conditions was chosen because TNF-α+IFN-γ application is a well-studied priming method, liver represents a non-primary lesion organ in colitis, and low and high concentrations of colon homogenate allow the study of concentration-dependent effects." (PMID 39176394, 2024). "Noteworthily, YOD1 was mainly expressed in IECs under physiological conditions, but deletion of YOD1 had no impact on TNF-α-induced apoptosis of IECs, implying that YOD1 in IECs may be dispensable for colitis." (PMID 39333628, 2024). "This could be the reason why the inhibition of MyD88 failed to mitigate the severity of colitis, as evaluated by DAI, HS, and several proinflammatory cytokines, including IL-1β, IFN-γ, and TNF-α." (PMID 38946731, 2024). "Based on data supporting the use of tumor necrosis factor (TNF) inhibitors in the steroid-sensitive setting and clinical practice, infliximab was used to manage the immune-mediated TRAE of diarrhea/colitis in this study even in the non-refractory low-grade setting." (PMID 38871975, 2024).